NF2 (NF2, moesin-ezrin-radixin like (MERLIN) tumor suppressor)
Diseases named in the same sentence as NF2 in open-access papers (continued):
Sharing a sentence is not in itself a finding about the gene and the disease.
tumor (continued). "Utilizing genetically engineered mouse models of tumor specific manifestations of both NF1 and NF2, and appropriate cell lines, the preclinical consortium has focused on screening and testing potential therapeutic options of reach tumor type." (PMID 34885143, 2021). "NF2 is a tumor suppressor gene comprised of 17 exons with 2 splicing isoforms that is positioned on chromosome 22q12.2." (PMID 33445724, 2021). "In terms of proliferation, Rac1 has been reported to promote SC proliferation by suppressing NF2; however, this leads to tumor formation, which often results from an unsuccessful nerve regeneration." (PMID 34062912, 2021). "Merlin, originally identified as the product of the tumor suppressor gene, Nf2, is a component of the apical membrane actin cytoskeleton that has been identified as an upstream regulator of Hippo–YAP signaling pathway." (PMID 34058200, 2021). "The tumor suppressor activity of NF-2 is mediated in part by downregulating interactions with FAK signaling, and tumor cells with NF-2 inactivation or q22 deletion have been shown to respond to FAK inhibition." (PMID 34638590, 2021). "As will be discussed later, there are clinical trials ongoing utilizing FAK inhibitors in NF-2 mutated tumors due to the importance of FAK signaling in the tumor suppressor activity of NF-2." (PMID 34638590, 2021). "In the Nf2‐deleted mammary glands, tumor latency was shorter ‐ at day 56, 50% of the mice in the Nf2−/− MMTV Neu + group were tumor‐free, while that mark was hit at day 74 for the control group." (PMID 33410252, 2021). "Of note, redox homeostasis can be disrupted by TAZ inhibition-induced metabolic reprogramming in NF2-mutant tumor cells." (PMID 33499877, 2021). "Alteration in NF2 function has been recently related to the tumor immune microenvironment and proposed as biomarker for MPM patient’s stratification for immune-checkpoint blockade (ICB) therapies." (PMID 34830817, 2021). "NF-2 is located on chromosome 22q12.2 and codes for the Merlin protein which is a cytoskeletal protein and also has tumor suppressor activity." (PMID 34638590, 2021). "The intensity of 4‐HNE detection was significantly greater in Nf2−/− MMTV Neu+‐derived tumor tissue, indicative of an increased oxidative stress in these tumors that developed with shorter latency." (PMID 33410252, 2021). "A previous study indicated that TAZ deficiency induced a transition in the metabolic phenotype and ROS accumulation in NF2-mutant tumor cells, rendering tumor cells more vulnerable under nutrient stress." (PMID 33499877, 2021). "It has been reported that in BNC mice, where the specific disruption of the Bap1, Nf2, Cdkn2ab tumor suppressor loci in the mesothelial lining of the thoracic cavity leads to a highly aggressive MM, an infiltration of leukocytes was found." (PMID 34830817, 2021). "In the late stage of tumor progression (day 28), there was a reduction in the levels of Csf1, Mmp14, Nedd9, Nf2, Plaur, and Tgfb1 genes by all the investigated compounds." (PMID 32887237, 2020). "Taken together, treating NF2 VS primarily with radiotherapy suggests that this treatment works best for tumor control and FN preservation and has a minor effect on hearing preservation." (PMID 32244314, 2020). "Previous studies have shown that CUL4 ubiquitin ligase complex is one of the pathways being unleashed when the key tumor suppressor for MPM, NF2, is mutated." (PMID 33233664, 2020). "Recently, in our hospital, a clinical trial using a VEGFRs peptide vaccine was also conducted in patients with progressive neurofibromatosis type 2 (NF2)-derived schwannomas, showing hearing improvement and tumor volume reduction." (PMID 32887369, 2020). "Nf2 heterozygous mice developed a variety of malignant tumors which was highly metastatic, confirming the role of merlin as a tumor suppressor." (PMID 33171868, 2020).
tumor (continued). "The NF2 gene product, Merlin, is a tumor suppressor classically known for its ability to induce contact-dependent growth inhibition." (PMID 32299434, 2020). "Small cohorts of patients treated with bevacizumab have shown improvement in symptoms and limited efficacy in reducing tumor size and growth in a subset of NF2 patients, though further studies in large randomized cohorts are needed." (PMID 31161239, 2020). "Our exploratory clinical trial also demonstrated that VEGFRs peptide vaccination showed hearing improvement and tumor volume reduction in NF2 patients." (PMID 32887369, 2020). "In pRCC2 tumors, we observed a SMARCB1 driver mutation in one pRCC2; TERT promoter in two pRCC2; SETD2, PBRM1 and NF2 in one pRCC2 tumor each." (PMID 32555180, 2020). "Genomic investigation of these tumors revealed that somatic inactivation of NF2 is the principal and perhaps the only driver of tumor initiation; and that tumor progression likely occurs via accumulation of CNVs, rather than point mutations." (PMID 32724039, 2020). "It has been shown that MYPT1 is a regulatory subunit of the PP1A enzyme, which targets NF2, whose dephosphorylation at serine 518 is the initial step in the Hippo pathway, resulting in growth arrest and tumor suppression." (PMID 31926547, 2020). "The resection of NF2 VS can be more difficult than sporadic ones because the tumor tends to be more adherent to adjacent structures." (PMID 32244314, 2020). "Other work has recently demonstrated cooperation between Nf2 and Cdkn2a in MM development in asbestos-exposed Nf2+/−;Cdkn2a+/− mice, which exhibited significantly hastened tumor onset and disease progression vs. similarly exposed Nf2+/− and wild-type cohorts." (PMID 32117751, 2020). "Our study confirm the importance of Hippo core pathway member YAP1, but also of upstream effector NF2 for the regulation of tumor morphology and invasive properties." (PMID 31959902, 2020). "NF2 is mutated in 19% of MPM, and the chromosomal region 22q containing this gene is commonly lost in MPM tumor tissues." (PMID 33233664, 2020). "Tenascin-C (TNC) has been demonstrated to have an angiogenic role in GBM; ezrin to inhibit NF2 tumor-suppressor in GBM." (PMID 33374813, 2020). "The vast majority of our non-NF2 mutant tumours occurred in female patients, and all these tumours were WHO grade I tumours." (PMID 32070062, 2020). "NF1 and NF2 have been critical models in the study of cancer, with each yielding numerous insights into the biology of neoplasia and genetic inheritance." (PMID 31161239, 2020). "Both Neurofibromatosis 1 and 2 (NF1 and NF2) are disorders characterized by the formation of tumours of the peripheral and central nervous system, primarily affecting cells of neural crest origin." (PMID 31730023, 2019). "Chromosomal loss was most frequent (89%) at chromosome (chr) 22q, where the well-known tumor suppressor NF2 is located." (PMID 31470906, 2019). "Our current studies also confirmed the effect of STX3451 and STX2895 on microtubules in NF2-null tumour cells." (PMID 31730023, 2019). "In this study, we demonstrate VEGFRs expression in endothelial cells and tumor cells in NF2 schwannomas, and conduct an exploratory clinical investigation of VEGFRs peptide vaccination in patients with progressive NF2." (PMID 31848332, 2019).
tumor (continued). "Although mutations at the NF2 locus are rare (~ 10%) in human PDAC 12, 19, Merlin expression is lost in > 40% of PDAC and is negatively correlated with tumour stage, regional lymph node metastasis and differentiation." (PMID 31330086, 2019). "Although malignant transformations of NF2 tumours are rare, better therapeutics are needed, because numerous tumours can lead to early morbidity and early mortality (age 36)." (PMID 31730023, 2019). "In one NF2-mutated IVM WHO°I, we detected two missense mutations (V1943I and V1961I) in the Adenomatous polyposis coli (APC) gene, which is a crucial tumor suppressor in the WNT/b-Catenin pathway." (PMID 31470906, 2019). "STX2895 and STX3451 treatment on NF2 null (−/−) cell lines induces nuclear fragmentation, microtubular disruption, inhibition of cellular migration/wound healing, and can induce apoptosis in both benign and malignant NF2 tumour-derived cells." (PMID 31730023, 2019). "Of the 4 agents we tested, STX2895 was the most robust for inducing apoptosis in NF2 tumour cell lines." (PMID 31730023, 2019). "Among these spurious candidates were predicted pathogenic mutations in known oncogenic and tumor-suppressor genes, such as ALK and NF2, potentially confounding patient diagnosis." (PMID 30902988, 2019). "We performed a multivariate analysis, including gender, ASA-intake, prior RT and presence of NF2, tumor extension together with patient age and MIB1 expression." (PMID 31291992, 2019). "Here, the authors show that VEGFRs peptide vaccination can improve hearing and reduce tumor volume in NF2 patients, including in previously bevacizumab resistant tumors." (PMID 31848332, 2019). "Both STX3451 and STX2895 provide new approaches for inducing cell death and lowering tumour burden in NF2 as well as in NF1, which both have limited treatment options." (PMID 31730023, 2019). "While the ABI was originally designed for NF2 patients, recent studies suggest a possible role of this technology to provide hearing in non-tumor children and adults." (PMID 30760974, 2019). "NF2 and POLE driver mutations were each present in 13 (34%) and 12 (32%) of the 38 total primary and recurrent tumor samples, respectively." (PMID 31191822, 2019). "Such genetic mouse MM models include mice heterozygous for NF2, one of the most often altered tumor suppressor genes with up to 44% alterations in human MM cell lines." (PMID 29928505, 2018). "Asbestos-exposed Nf2 (+/−) knockout mice have resultantly been shown to exhibit markedly accelerated MM tumor formation compared to their asbestos-treated wild-type littermates." (PMID 29565815, 2018). "MLN4924, a NEDD8-activating enzyme (NAE) inhibitor, has been shown to suppress CRL4DCAF1 and attenuate YAP1 activation in NF2-mutant tumor cells." (PMID 29565815, 2018). "Together, these findings indicate that NF2 and LATS2 mutations can be coincident in a given MM tumor." (PMID 29565815, 2018). "Although heterozygous losses or inactivating mutations at the NF2 locus occur in approximately 10% of human PDAC, merlin expression is lost in >40% of PDAC, and is negatively correlated with tumour stage, regional lymph node metastasis and differentiation." (PMID 30428574, 2018). "Additional studies showed that Nf2 is one of the most frequently mutated tumor suppressor genes in PeM, and that asbestos-exposed Nf2 knockout mice exhibited accelerated MM tumor formation." (PMID 30022998, 2018). "Although MLN4924 alone did not exhibit significant preclinical activity, administering MLN4924 with the mTOR/PI3K inhibitor GCD-0980 suppressed the growth of NF2-mutant tumor cells in vitro as well as in mouse and patient-derived xenografts." (PMID 29565815, 2018). "In some instances of cancer, it has been shown that inactivity of upstream Hippo pathway members (e.g., through mutations in NF2/MERLIN, LATS1, LATS2 or SAV1) can lead to over-activity of YAP/TAZ, which can lead to tumour initiation." (PMID 29534050, 2018).
tumor (continued). "A germline perturbation affecting NF1 or NF2 can be considered a tumor initiation event, explaining why this germline disorder guarantees the formation of multiple benign nerve sheath tumors over one’s lifetime." (PMID 29616301, 2018). "The fact that nearly all patients with NF1/NF2 develop one or more benign tumors can be understood by acknowledging that in these disorders a germline tumor initiation event is involved." (PMID 29616301, 2018). "Immunohistochemical staining of spontaneous and NF2-related VS suggested a correlation between tumor proliferation and COX-2 expression." (PMID 29416648, 2018). "Several key genetic alterations are associated with the development and progression of MM including mutations of the CDKN2A/ARF, NF2, and BAP1 tumor-suppressor genes." (PMID 29565815, 2018). "Chromosome 22q contains several known tumor suppressors, such as NF2, CHEK2 and SMARCB1, and all the three tumor suppressors were deleted in the three cases." (PMID 28177878, 2017). "In rare cases, they occur as bilateral tumours within the context of the inherited familial cancer syndrome Neurofibromatosis Type 2 (NF2)." (PMID 28710469, 2017). "We are also interested in the implications of protein/mRNA expression and tumour-cell proliferation in response to different NF2 gene statuses." (PMID 28710469, 2017). "On further evaluations it was confirmed that the patient was a case of NF2 with bilateral tumours, right being larger than the left." (PMID 27174775, 2017). "Consistent with findings in GBM tumour tissues, NF2 and DNMT1 levels were decreased and increased, respectively, in these cells." (PMID 28764788, 2017). "Previously, in a genetically engineered MM mouse model, heterozygous for Nf2+/−, a high rate of homozygous deletion of Cdkn2a was observed in MM tumours induced by asbestos exposure." (PMID 28577549, 2017). "Consistent with the previous finding, four out of the five NF2-related tumours in this study were found to have an exon 1 deletion by Dosage Analysis." (PMID 28710469, 2017). "Of the 18 NF2 alterations, 89% were inactivating frame-shift, splice site, or nonsense alterations, consistent with the known tumor suppressor role of NF2, compared with only 16% of non-NF2 mutations (p = 6 × 10−10)." (PMID 28713588, 2017). "When asked the nature of the NF2-related problem that the registrant considered major, hearing difficulty was by far the most commonly indicated (33% of the 579), followed by tumor burden (13.6%), dizziness (12.3%) and pain (11.9%)." (PMID 28644838, 2017). "Cells with high OCT4/SOX2 levels were resistant to chemotherapy, barely affected by re-expression of the NF2 tumour suppressor, and had a high-tumour initiating capability in vivo." (PMID 29100460, 2017). "The oncogene JAK1 contained a high impact mutation within aggressive PET-10 tumor, while high impact mutations were identified in CARD11, NF2 and ORC1 within aggressive PET-20, and in DPY19L2 and SNRPC within non-aggressive PET-24." (PMID 29100308, 2017). "Inactivation and downregulation of the tumour suppressor NF2 has been widely recognized as a critical contributor to GBM." (PMID 28764788, 2017). "Overall, primary atypical NF2 tumours were significantly more likely to be CNV-high, as compared with benign NF2 ones (P=0.02, Student’s t-test)." (PMID 28195122, 2017). "NF2 is a tumour suppressor involved in regulating intracellular signalling pathways and cell cycle progression." (PMID 28821767, 2017). "Taken together, these data demonstrate that crizotinib has significant anti-proliferative activity against NF2-null Schwann cells in vitro and anti-tumor activity in vivo." (PMID 27363027, 2016). "We identified crizotinib, a MET and ALK inhibitor, as a potent inhibitor of NF2-null Schwann cell proliferation in vitro and tumor growth in vivo." (PMID 27363027, 2016).
tumor (continued). "Studies linking the NF2 tumour suppressor as a modulator of growth factor and extracellular matrix signals that trigger Rac1-dependent cytoskeleton-associated processes indicate its important role in the processes of cell adhesion and migration." (PMID 27429002, 2016). "Towards this goal we employed pharmacologic and genetic approaches to inhibit MET and identified the FDA approved drug crizotinib (PF-2341066), as a potent inhibitor of tumor progression and cellular proliferation of NF2-null Schwann cells." (PMID 27363027, 2016). "Post-RT outcomes for patients with NF2 are inferior to those for sporadic patients, with short-term local tumor control rates around 80-85% and hearing preservation rates less than 50%3." (PMID 28191549, 2016). "The first animal model in the field bearing a Schwann cell-specific ablation of the tumor suppressor produced NF2-related tumor formation in mice." (PMID 27236462, 2016). "We found that CD44 depletion leads to decrease of p-NF2 and p-NF2/NF2, indicating the activation the tumor suppressor function of NF2." (PMID 25605020, 2015). "We isolated a primary tumor obtained after repeated injection of asbestos fibers in the peritoneum of an Nf2+/− mouse." (PMID 25877069, 2015). "Potential tumor suppressor genes located within 22q12 include NF2, which exhibits markedly reduced mRNA expression in SEPN." (PMID 25909290, 2015). "The most common reason for implanting an ABI is damage to the auditory nerve, for example as a result of tumour removal in patients with neurofibromatosis type II (‘NF2’)." (PMID 26138501, 2015). "In contrast to CI users, open-set speech perception for ABI users with NF2 is usually very poor, although better overall outcomes have been reported for patients with non-tumour aetiologies and for a minority of NF2 patients." (PMID 26138501, 2015). "We found that CD44 depletion leads to decrease of p-NF2 and p-NF2/NF2, indicating the activation of the tumor suppressor function of NF2." (PMID 25605020, 2015). "Merlin, a tumor suppressor and the protein product of the NF2 gene, plays important role in inhibition of cell proliferation and progression through the G1 phase of the cell cycle." (PMID 26460955, 2015). "Concordantly, NF2 acts as a tumor suppressor through Hippo signaling in mice, where conditional knockout of NF2 in mice liver resulted in HCC." (PMID 25097728, 2014). "In a study of ten NF2 patients treated with bevacizumab, nine had tumor shrinkage, and seven experienced hearing improvement." (PMID 24393766, 2014). "In a huge clinical study, peripheral nerve lesions unrelated to tumor masses were observed in 6% of patients suffering from NF2." (PMID 25012216, 2014). "In primary tumor and meningioma cell lines, YAP overexpression and nuclear localization have been found in cells with merlin loss (NF2 mutation)." (PMID 25485306, 2014). "A recent application for WB-MRI includes the detection of peripheral nerve sheath tumors (PNSTs) and the assessment of tumor burden in syndromes with a predominance of multifocal PNSTs, such as the NF syndromes, including NF-1, NF-2, and schwannomatosis (SWN)." (PMID 24967287, 2013). "Theories on the tumor suppressive roles of NF2 have largely been restricted to its actions as a scaffolding protein, however NF2 can be found in the nucleus, where its nuclear localization appears to be mediated by the cell cycle." (PMID 23308224, 2013). "In turn, important targets are induced such as those encoding proteins involved in tumor progression and angiogenesis (PAI-RBP1), tumor suppression (NF2, LKB1), cell–cell adhesion (α-catenin), or cytoskeleton dynamics (tubulin α-6)." (PMID 23715860, 2013).